PDK4 (pyruvate dehydrogenase kinase 4)
Diseases named in the same sentence as PDK4 in open-access papers (continued):
Sharing a sentence is not in itself a finding about the gene and the disease.
tumor (111 papers, 2013 to 2026). "While animals exposed to cisplatin did not have higher stage tumors, they still had larger bladders than their WT counterparts, further confirming the possibility that PDK4−/− animals are more predisposed to tumor progression." (PMID 36980540, 2023). "High expression of PDK4 has been associated with altered metabolic pathways in tumor cells, including lactic acidification and malignant transformation." (PMID 37398672, 2023). "Taken together, not only is PDK4 associated with the glycolysis and proliferation of neoplasm but also it exerted an effect on the development and prognosis of neoplasm." (PMID 34220962, 2021). "Since low levels of PDK4 result in enhanced OXPHOS and/or enhanced lipogenesis, both of which are associated with poor prognosis in PCa, PDK4 should have a tumor suppressive effect in primary PCa." (PMID 33384955, 2020). "Significantly, we observed widespread loss of PDK4 expression in tumor cells compared to normal tissue." (PMID 25379179, 2014). "In our study, the positive expression of PDK4 in Cluster_2 may suggest that the tumor type in these patients is associated with aberrant tumor cell metabolism." (PMID 37398672, 2023). "This could be further honed to different cellular populations to provide a robust and granular explanation as to which cells are most effected by loss of PDK4 and how this promotes tumor formation." (PMID 36980540, 2023). "Functionally, human studies on HCC indicate that loss of PDK4 is associated with more advanced tumors and worse outcomes, supporting the idea that PDK4 may function as a tumor suppressor." (PMID 36980540, 2023). "If loss of PDK4 prevents normal mitochondrial fission, this may constrain tumor growth by increasing mitochondrial instability, thereby limiting cell proliferation." (PMID 36980540, 2023). "We hypothesized that PDK4 deficiency would reduce tumor formation and enhance cisplatin efficacy based on these data." (PMID 36980540, 2023). "Experiments with chronic genetic loss of PDK4 indicate that it may have tumor-suppressive functions, whereas, acute inhibition of all PDKs with agents such as DCA yields a therapeutic effect based on prior experiments." (PMID 36980540, 2023). "We next sought to determine whether PDK4 deficiency would alter late-stage tumor formation or progression." (PMID 36980540, 2023). "Future studies should delineate what is the precipitating factor for loss of PDK4 that occurs during tumor formation and whether this is functionally related to more aggressive tumor outcomes." (PMID 36980540, 2023). "Besides that, the association existing in PDK4 expression and tumor-infiltrating immune cells was evaluated." (PMID 34220962, 2021). "Importantly, PDK4 expression exhibited a large association with the grade of tumor (P = 0.0064)." (PMID 34220962, 2021). "The overexpression of miR-122 effectively reversed the effects of overexpressing PDK4 on these indicators of the tumor tissue (P<0.0001)." (PMID 40969279, 2025). "It was reported that PDK4 facilitates tumor cell proliferation, invasion, glycolysis, and chemotherapy resistance in OC." (PMID 40969279, 2025). "Reduced expression of PDK4 has been shown to divert glucose metabolism towards the TCA cycle during epithelial–mesenchymal transition (EMT) in tumor cells." (PMID 40801609, 2025). "We reported that retrodifferentiation of human tumour-derived hepatocytes into CSCs leads to an upregulated expression of pyruvate dehydrogenase kinase 4 (PDK4), which prevents pyruvate from feeding the tricarboxylic acid (TCA) cycle." (PMID 41249163, 2025). "In the regulation of glycolysis of tumor cells, depletion of PDK4 reduces glucose consumption, lactic acid, and ATP production." (PMID 40969279, 2025). "In vivo and in vitro, the overexpression of PDK4 and miR-122 effectively abolished the effects of OA and the overexpression of PDK4 on OC cells and tumor tissue, respectively." (PMID 40969279, 2025).
tumor (continued). "Overexpressing PDK4 effectively reversed the effects of OA on the volume and weight of tumor tissue (P<0.0001)." (PMID 40969279, 2025). "Meanwhile, overexpressing PDK4 reversed the inhibition of tumor volume and weight, Ki67 expression, and glycolysis, and the promotion of pathological injuries and autophagy of tumor tissue induced by OA in vivo." (PMID 40969279, 2025). "The overexpression of PDK4 and miR-122 effectively reversed the effects of OA and the overexpression of PDK4 on the Ki67 expression in the tumor tissue, respectively (P<0.01)." (PMID 40969279, 2025). "For example, ARSG, CTH, PDK1, and PDK4 are heavily involved in cellular metabolism and oxidative stress regulation, pathways tightly coupled with tumor proliferation and survival under adverse microenvironmental conditions." (PMID 41153607, 2025). "In vivo xenograft tumor models further confirmed that PCAT19 knockdown significantly reduces tumor growth, increases miR-182 levels, and decreases PDK4 expression and PDHE1α phosphorylation." (PMID 39744012, 2024). "In conclusion, our results confirmed the ability of G-Rh2 to target at the PDK4 locus, providing molecular evidence for altered tumor biometabolic behavior." (PMID 38671369, 2024). "Surprisingly, we observed downregulation of Pdk4 in mice with TNBCs, but its upregulation in skeletal muscle of ER+/PR+ and ER+/PR− tumor-bearing mice." (PMID 38651826, 2024). "Our findings suggested that circFTO regulated tumor progression and aerobic glycolysis through the miR-148a-3p/PDK4 axis." (PMID 38554157, 2024). "It was found that in resistant tumor tissues, PDK4 localization includes both the cytoplasm and the nucleus." (PMID 39004737, 2024). "It further suppressed aerobic glycolysis, promoted mitochondrial aerobic oxidative process, and stimulated the production of ROS to promote tumor cells to enter the normal apoptotic program through PDK4 regulation." (PMID 38671369, 2024). "G-Rh2 has been shown to target HIF-1α and downregulate PDK4 expression, thus inhibiting tumor glycolysis." (PMID 38671369, 2024). "To explore the distribution of PDK4 among tumor cell clusters, we further extracted malignant B cells for dimensionality reduction and clustering." (PMID 39004737, 2024). "Targeting PDK4 to inhibit tumor glycolysis and restore mitochondrial oxidative phosphorylation function has become a hotspot for tumor therapy and an important target for clinical treatment, attracting high attention." (PMID 38671369, 2024). "We investigated the impact of G-Rh2 on the malignant progression of NSCLC and how it regulated PDK4 to influence tumor aerobic glycolysis and mitochondrial function." (PMID 38671369, 2024). "Conversely, PDK4 knockdown by shRNA from these PSC27PDK4 cells before xenograft implantation markedly reduced tumor volumes (P < 0.01 and P < 0.05, respectively)." (PMID 37903887, 2023). "Given the recent identification of alternate substrates of PDK4, understanding how it affects tumor formation both in the context of PDH and in the context of its other substrates is imperative." (PMID 36980540, 2023). "The data showed that the presence of senescent stromal cells markedly accelerated tumor growth, a tendency albeit significantly retarded upon PDK4 knockdown from stromal cells." (PMID 37903887, 2023). "PDK4−/− animals had larger tumors than their WT counterparts after 7 w of additional tumor growth as assessed by bladder weights, which is a surrogate for tumor volume (23 w in total)." (PMID 36980540, 2023). "Upregulation of PDK4 mediates aerobic glycolysis (the ‘Warburg effect’), favors tumor growth and promotes apoptosis resistance; however, potential implications of PDK4 in senescence-associated phenotypes remain hitherto underexplored." (PMID 37903887, 2023). "Mechanistic studies investigating the effects of PDK4 on these proteins are needed to better understand how PDK4 suppresses tumor formation." (PMID 36980540, 2023).
tumor (continued). "Tumor staging based on H&E staining yielded a significant increase in tumor stage in PDK4−/− animals compared to WT controls." (PMID 36980540, 2023). "The expression pattern of these factors was largely consistent with that of senescence markers p16INK4a and p21CIP1 in tumor foci, suggesting an inherent correlation of PDK4 induction with cellular senescence and the SASP." (PMID 37903887, 2023). "This is notable because we found that the tumor suppressive effects of PDK4 are most noticeable in later stages of tumor formation in mice." (PMID 36980540, 2023). "PDK4 is a metabolism gene that promotes tumor development, and acts as a prognostic biomarker in ccRCC." (PMID 37715154, 2023). "We also noticed 18 Hox genes, Mmp13, Tbx, Pdk4, Bmp and other proven tumor-related genes in the list." (PMID 37696812, 2023). "This was consistent with increased methylation of the PDK4 promoter in TCGA tumor specimens compared to controls, suggesting a potential epigenetic mechanism of PDK4 suppression." (PMID 36980540, 2023). "Gene expression data of microdissected stroma from normal breast and TNBC31 showed significant downregulation of PDK2 and low levels of PDK1, PDK3 and PDK4 in the tumour stroma similarly to our CAFs." (PMID 35760868, 2022). "Possible mechanisms mediating the role of PDK4 accrue to the regulatory function in tumor metabolism and the tumor microenvironment." (PMID 35626257, 2022). "Our data were in line with the results of the database—that is, PDK4 expression was significantly downregulated in GC tissues compared to non-tumor tissues." (PMID 35626257, 2022). "After collecting the tumor samples, we analyzed the protein expression of PDK4, p-ERK, p-SRC, and p-JNK by IHC staining." (PMID 36362028, 2022). "We thought that the lower expression levels of PDK4 in tumor stromal cells and infiltrating immune cells decreased tumor purity with increased PDK4 expression, interfering with the consistency of results in GC cells and in GC tissues." (PMID 35626257, 2022). "Regulation of PDK4 was an important regulator of ferroptosis resistance in carcinogenesis and tumor progression." (PMID 36478991, 2022). "In line with our in vitro data, PDK4 was increased at both gene and protein levels in the tumor hosts, whereas MitoQ partially prevented PDK4 overexpression." (PMID 35392166, 2022). "To clarify the effect of PDK4 in vivo, we used a xenograft model that showed reduced tumor size in PDK4 knockdown cells." (PMID 36362028, 2022). "Our ESTIMATE algorithm revealed that PDK4 expression positively correlated with stromal, immune and ESTIMATE scores of GC, which means tumor purity was low in GC samples with high PDK4 expression." (PMID 35626257, 2022). "Transcriptomics + Proteomics + Metabolomics:High STAT3 expression → OXPHOS downregulated (Transcriptomics).High STAT3 expression → TCA cycle/OXPHOS downregulated (Proteomics).High PDK4 expression → inhibited PCa tumor growth." (PMID 35736421, 2022). "The tumor sizes of the control and PDK4 knockdown groups were 1300.573 mm3 and 772.085 mm3, respectively, at the end of the experiment." (PMID 36362028, 2022). "Inhibition of PDK4 suppressed migration and invasion in vitro and tumor growth in vivo through the extracellular signal-regulated kinase (ERK), SRC, and JNK pathways." (PMID 36362028, 2022). "Seven days after injection, the differences in tumor size between the wild-type and PDK4-inhibited cells were significant." (PMID 36362028, 2022). "We also identify transcriptomic changes induced by miR-32 in tumor-containing prostates and identify PDK4 as a target of miR-32 relevant for human PC." (PMID 35228520, 2022). "That’s why we supposed that PDK4 expression levels in non-tumor cells are inhibited, which is in contrast with those in tumor cells." (PMID 35626257, 2022). "The hidden links between PDK1, PDK2, PDK3, and PDK4 expression and tumor-infiltrating immune cells in GC were assessed by the TIMER database." (PMID 34220962, 2021).
tumor (continued). "Pyruvate dehydrogenase kinase 4 functions as a positive regulator of glycolysis during tumor development." (PMID 34252986, 2021). "Collectively, our data suggested that PDK4, along with the co-expressed genes, probably participated in immune response in the microenvironment of tumor via exerting an effect on immune cells, especially macrophages." (PMID 34220962, 2021). "The PDK4 OE tumors that developed in untreated mice were larger than the EV tumors (tumor weight, 0.042; tumor volume, P = .0034)." (PMID 34252986, 2021). "Here, we identify and characterise tumour subsets from ascites-derived tumour cells with stemness, metastasis and metabolic switch properties and to delineate the involvement of pyruvate dehydrogenase kinase 4 (PDK4) in such process." (PMID 32390009, 2020). "In conclusion, we demonstrated for the first time that PDK4 plays a tumor-suppressing role in the pathogenesis of HCC." (PMID 32489458, 2020). "Collectively, these findings demonstrate that depletion of endogenous PDK4 markedly accelerated tumor growth in vivo." (PMID 32489458, 2020). "While PDK4 and PDK2 are expressed at lower levels, PDK1 and PDK3 are supposedly overexpressed in PCa and associated with advanced tumor stages." (PMID 33384955, 2020). "Owing to predominant localisation in the cytoplasm, PDK4 staining was stronger in malignant tumour tissues relative to normal ovarian tissues/benign tumours (p < 0.01)." (PMID 32390009, 2020). "Significant PDK4 mRNA expression was additionally detected in tumourspheres cultured from ascites-derived tumour cells and OVCAR3." (PMID 32390009, 2020). "In conclusion, we have demonstrated enhanced CSC characteristics and PDK4 overexpression in ascites-derived tumour cells." (PMID 32390009, 2020). "A recent study revealed that PDK4 induces tumour growth through regulating the KRAS pathway in lung and colorectal tumours." (PMID 32390009, 2020). "The correlations between expression level of PDK4 and GC patients' clinical features also revealed a highly positive relationship between PDK4 expression and tumor size." (PMID 32780563, 2020). "Consistently, xenograft model confirmed that over expression of PDK4 can attenuate the suppression effect of Mettl3Mut/- HeLa cells on in vivo tumor growth." (PMID 32444598, 2020). "Our findings clearly suggested that ascites-derived tumour cells displayed CSC properties with increased PDK4 expression." (PMID 32390009, 2020). "IHC showed that Mettl3 depletion led to a lower level of PDK4 in xenograft tumor tissues, which suggested that deletion of Mettl3 can regulate the expression of PDK4 in vivo." (PMID 32444598, 2020). "In contrast to other PDK isoforms, not only oncogenic, but also tumor suppressive functions of PDK4 have been reported." (PMID 33384955, 2020). "In contrast to PDK1–3, data suggest either oncogenic or tumor suppressive function of PDK4, dependent on the metabolic profile of the tumor." (PMID 33384955, 2020). "In order to assess its putative clinical significance, PDK4 expression in the diverse tumour and normal tissue compartments was correlated with oncologic outcome data." (PMID 30808993, 2019). "Immunohistochemistry confirmed more abundant expression of PDK4 protein in healthy mucosa tissue than in primary tumour tissue." (PMID 30808993, 2019). "Expression analysis of PDK4 in patients undergoing surgical resection of CRLM (CRLMx cohort) revealed that PDK4 mRNA expression was consistently higher in tumour-surrounding liver tissue than in tissue derived from corresponding CRLM." (PMID 30808993, 2019). "Regarding individual gene expression during this recovery period, we noted significant downregulation of Pdk4 and Rasd1, both identified as inactivated tumor suppressor genes in a global DNA methylation study." (PMID 28575117, 2017). "The fact that PDK4 emerged as a key factor during EMT in our study further establishes the role of this enzyme in regulating ECM/tumor crosstalk and bioenergetics." (PMID 25379179, 2014).
tumor (continued). "The mining of microarray data from a human HCC data set revealed that PDK4 mRNA is significantly down-regulated in liver tumors compared to adjacent non-tumor liver tissues (0.66-fold, P = 3.11E-85)." (PMID 24376596, 2013). "Overexpression of PDK4, induced by TOP1MT deficiency, drives tumor metastasis." (PMID 41220952, 2025). "High expression of PDK4 was associated with negative prognostic factors such as the presence of lymph node metastasis, high tumor grade, vascular invasion, poor disease-free and metastasis-free survival and association with DNA replication and repair." (PMID 40801609, 2025). "Analysis of human tumor samples showed that PDK4 expression was downregulated in most tumor types." (PMID 40801609, 2025). "Our preliminary research has found that G-Rh2 can potentially serve as an inhibitor of PDK4, thereby inhibiting tumor glycolysis, promoting mitochondrial oxidative phosphorylation, contributing to the benign transformation of tumors, and inducing tumors to enter the normal apoptotic program." (PMID 38671369, 2024). "Similarly, downregulation of pyruvate dehydrogenase kinase 4 (PDK4) reverted the inhibition of the pyruvate dehydrogenase complex and reduced cell proliferation and tumor volume, potentiating cisplatin effects both in vitro and in vivo." (PMID 38611096, 2024). "Thus, stromal PDK4 expression in senescent cells represents an important force driving tumor progression in vivo." (PMID 37903887, 2023). "This supports the idea that the loss of PDK4 is associated with tumor formation and not just the inflammatory phase of BBN or the precancerous phase." (PMID 36980540, 2023). "The in vitro results prompted us to further determine whether PDK4 induction occurs within the tumor microenvironment (TME), a pathological entity where many benign stromal cells reside." (PMID 37903887, 2023). "Moreover, HK2, MMP11, CDH3, PDK4, SERPINB5, and SLC2A1 expression were closely associated with tumour stages." (PMID 37234801, 2023). "Importantly, through the use of a tumor microarray, we were able to show that PDK4 protein is also reduced in BCa tissue compared to control tissue from a commercially available tumor microarray using human samples." (PMID 36980540, 2023). "The totality of these data indicate that PDK4 specifically may function as a tumor suppressor in BCa, particularly in later-stage tumors." (PMID 36980540, 2023). "Selectively depleting or overexpressing PDK4 at specific points during tumor formation in mice may allow for a better understanding of how and when PDK4 yields its effects." (PMID 36980540, 2023). "Besides, PDK4 also plays an important role in survival, proliferation, invasion and metastasis of tumor cells." (PMID 37787988, 2023). "In summary, PDK4 has a complex, multifunctional role in BCa and may represent an underrecognized tumor suppressor." (PMID 36980540, 2023). "Our initial hypothesis was that PDK4−/− animals would exhibit reduced tumor formation and be more responsive to cisplatin based on prior in vitro data in BCa, in addition to numerous studies demonstrating an antitumorigenic effect of PDK inhibition." (PMID 36980540, 2023). "However, in contrast to other PDK isoforms, not only oncogenic, but also tumor-suppressive functions of PDK4 have been reported [reviewed in 39]." (PMID 35228520, 2022). "However, the expression of PDK4 varies greatly in different tumors, and its tumor-promoting and tumor-inhibiting effects are still unclear." (PMID 35757505, 2022). "LncRNA AFAP1-AS1 serves as a tumor driver in the pathogenesis of OC via the miR-107/PDK4 axis." (PMID 33926489, 2021). "PDK4’s function is multifaceted, since it functions as both an oncogene and a tumor suppressor." (PMID 34589439, 2021). "Overexpression of PDK4 promoted cell proliferation, invasion, and tumor growth in vivo." (PMID 33833937, 2021). "PDK2 and PDK4 expression had shown a great correlation with tumor stage (P = 0.00289, P = 0.00431)." (PMID 34220962, 2021).